FRG2B (FSHD region gene 2 family member B)
Tractability: No criterion of Open Targets' tractability assessment is met for any kind of drug.
Gene: Protein-coding gene on chromosome 10 (133,623,895 to 133,626,795, reverse strand). Ensembl gene ENSG00000225899.
Subcellular location: Nucleus
Gene Ontology:
Cellular component: nucleus
Genetic constraint (gnomAD): Loss-of-function variants: 0 observed, 6.37 expected, observed/expected ratio (o/e) 0, 90% interval 0 to 0.47. That is too few expected variants to judge how well the gene tolerates losing a copy. Missense variants: 94 observed, 193.45 expected, observed/expected ratio (o/e) 0.49, 90% interval 0.41 to 0.58. Synonymous variants: 30 observed, 75.62 expected, observed/expected ratio (o/e) 0.4, 90% interval 0.3 to 0.54.
Homologues: Orthologues: mouse Frg2f1 (28% identical). Paralogues in human: FRG2 (99% identical), FRG2C (94% identical).